ALDH1A1 (aldehyde dehydrogenase 1 family member A1)
Diseases named in the same sentence as ALDH1A1 in open-access papers (continued):
Sharing a sentence is not in itself a finding about the gene and the disease.
lung carcinoma (continued). "To determine the CSCs, we used CSC markers CD133 and ALDH1A1, which are widely used in the case of lung cancer." (PMID 34832867, 2021). "In the literature, ALDH1A1 is post-transcriptionally regulated by SIRT-mediated deacetylation at Lys353 in lung cancer cells." (PMID 32977608, 2020). "The expression of ALDH1A1 is upregulated in endometrial carcinoma cells, and ALDH1A1 is a confirmed oncogene for lung cancer." (PMID 33490103, 2020). "For example, only CSCs that express aldehyde dehydrogenase 1 family member A1 (ALDH1A1) in lung cancer are resistant to gefitinib." (PMID 31461438, 2019). "TAZ induces lung cancer tumorigenesis by up-regulating Aldehyde Dehydrogenase 1 Family Member A1 (ALDH1A1)." (PMID 29642615, 2018). "We found that ALDH1A1 is highly expressed in lung carcinoma cell line A549 and EKVX, as well as in the large cell carcinoma cell line H460." (PMID 28978015, 2017). "Most significantly, inhibition of ALDH1A1 with its inhibitor A37 or CRISPR gene knockout in lung cancer cells suppressed lung tumorigenic and CSC phenotypes in vitro, and tumor formation in mice in vivo." (PMID 28415606, 2017). "Since TAZ and YAP have redundant function, we simultaneously knocked out TAZ alone or in combination with its paralog YAP in TAZ/YAP-high and ALDH1A1-high A549 human lung cancer cells using two single-guide RNAs (sgRNAs) targeting TAZ and YAP." (PMID 28415606, 2017). "Polymorphisms of ADH1C are associated with the risk of upper aerodigestive tract cancer, while ALDH1A1 expression has been found to be down-regulated in various types of lung cancer." (PMID 27738743, 2017). "More importantly, we found that ALDH positive lung cancer cells, marked by ALDH1A1, had lower levels of miR-218 and higher levels of STAT3 signaling than in ALDH negative cells." (PMID 28830450, 2017). "As CD133 and ALDH1A1 have been widely accepted as stem cell marker in lung cancer, we evaluated the expression of both proteins and found that both proteins were significantly downregulated in gigantol-treated cells." (PMID 26339272, 2015). "Other groups have detected ALDH1A1, ALDH1A2, ALDH3A1, and ALDH2A1 in lung cancers which were shown to have an association with chemoresistance." (PMID 24884875, 2014). "ALDH1A1 and ALDH3A1 were highly expressed in nonsmall cell lung cancer, and knock-down of these ALDH isoforms were associated with in vitro functional changes in the proliferation and motility of these cells." (PMID 23484127, 2013). "We utilized lysates from H522, a lung adenocarcinoma cell line that expresses high levels of ALDH1A1 to characterize the humoral immune response in lung cancer." (PMID 22110949, 2011). "ALDH1A1 was further explored as a tumor antigen that induces an autoantibody response in lung cancer." (PMID 22110949, 2011). "In addition, in vitro experiments showed that reducing ALDH1A1 weakens the growth and migration of some lung cancer cell lines, indicating its carcinogenic effects." (PMID 38589907, 2024). "ALDH1a1 has been implicated as an immunotherapy target in liver cancer through similar mechanisms as ALDH1a3 in sarcomas, suggesting that the immunotherapeutic-like effects of disulfiram in lung cancer may be due to ALDH1a1." (PMID 39133222, 2024). "The discrepancy between these two conclusions may be attributed to tumor cell heterogeneity, as different types of lung cancer cells may have distinct regulatory mechanisms for ALDH1A1 expression and function." (PMID 38589907, 2024). "The GAs of SWI/SNF complex may promote liver-specific metastasis by upregulating ALDH1A1 and APOBEC3B expression, providing novel insights into the molecular mechanisms underlying lung cancer liver metastasis." (PMID 37989338, 2023).
lung carcinoma (continued). "In addition, a greater percentage of ALDH1A1+ cells were present in gefitinib-resistant lung cancer cells." (PMID 37686694, 2023). "Compared to ALDH1A1− cells, ALDH1A1+ lung cancer cells were more resistant to gefitinib." (PMID 37686694, 2023). "Furthermore, TESC has been reported to promote lung cancer stemness by upregulating the expression of aldehyde dehydrogenase isoform 1A1 (ALDH1A1), a gene that is considered a predictor of poor prognosis for patients with PTC." (PMID 35173149, 2022). "S100A9 upregulates ALDH1A1 expression and activates the RA signaling pathway in lung cancer cells." (PMID 36387165, 2022). "Similarly, ALDH1A1 knockdown resulted in suppressed proliferative and migratory potential of lung cancer cells." (PMID 35173149, 2022). "had found that ALDH1A1 overexpression could reflect the poor historical subtype and advanced tumor grade in lung cancer patients." (PMID 35814382, 2022). "ALDH1A1, Nanog, Oct4, and Sox2 are reported stem cell markers in lung cancer." (PMID 34832894, 2021). "Finally, to confirm the in vitro and in vivo findings, we analyzed the expression of ZEB1, BMI1, and ALDH1A1 by immunohistochemistry in lung cancer specimens obtained from 20 NSCLC patients before treatment and after relapse during treatment with gefitinib." (PMID 33764690, 2021). "This may be due to the regulation of MALAT1 by ALDH1A1, as MALAT1 was reported to be regulated by ALDH1A1 in lung cancer." (PMID 32244924, 2020). "On the other hand, lung cancer exhibits a mixed feature of ALDH1A1 and ALDH1A3." (PMID 30220009, 2019). "To explore the utility of serum ALDH1A1 as potential biomarker for lung cancer, we tested ALDH1A1 protein levels in sera from 25 NSCLC patients with early-stage disease, 20 NSCLC patients with advanced stage disease, 17 patients with nonneoplastic pulmonary diseases and 9 healthy donors." (PMID 31534455, 2019). "We therefore examined the expression of ALDH1A1 across multiple lung cancer cell lines." (PMID 28978015, 2017). "It will be very interesting to further investigate how ALDH1A1 is only activated by TAZ in CSCs and whether high levels of TAZ is positively correlated with those of ALDH1A1 (CSC-specific) in clinical lung cancer patients." (PMID 28415606, 2017). "Next, we wished to further confirm our result in other lung cell lines and test whether endogenous TAZ is essential for activation of Aldh1a1 in lung cancers." (PMID 28415606, 2017). "Together, the data strongly supported NFATc2/SOX2/ALDH1A1 form a regulatory axis in lung cancer." (PMID 28737489, 2017). "To test whether activation of Aldh1a1 transcription by TAZ is due to activation of Aldh1a1 promoter, we performed a luciferase assay in H1299 human lung cancer cells using an ALDH1A1 promoter Gaussia luciferase reporter (ALDH1A1-Gluc)." (PMID 28415606, 2017). "ALDH1A1 was also found to be important in lung cancers, suggesting an important role in lung tumors.In this study, we verified the expression of ALDH1A1 in A549s cells and showed its markedly lower relative expression in A549 cells, where its expression is negligible." (PMID 24671051, 2014). "In order to evaluate whether sunitinib increases this cell population in lung cancer, we analyzed the presence of ALDH1A1-positive cells in tumors from mice bearing urethane-induced ADC and NTCU-induced SCC." (PMID 24500694, 2014). "We also report on the occurrence of an immune response to ALDH1A1 in lung cancer." (PMID 22110949, 2011). "In this study, we have used microarray analysis to assess global changes in gene expression that result from the knock-down of ALDH1A1 and ALDH3A1 in lung cancer cell line in order to gain insight into the underlying mechanisms that lead to up regulation of these two isozymes in some cancers." (PMID 19025616, 2008). "Thus, the decreased expression of ALDH1A1 in urethane-induced lung cancer may result from the urethane decreasing its expression via epigenetic alerions." (PMID 39272828, 2024).
lung carcinoma (continued). "Notably, lung cancer cells from clinical samples contained a significantly higher percentage of ALDH1A1+ cells that were resistant to epidermal growth factor receptor (EFGR) trypsin kinase inhibitor (TKI) and chemotherapy, manifesting one of the fundamental properties of CSCs." (PMID 35053430, 2022). "Among these, ALDH1, especially isoform ALDH1A1, is a key marker for CSCs in breast, prostate, colon, and lung cancer." (PMID 40665579, 2025). "The progression-free survival (PFS) analysis revealed that the ALDH1A1 high expression group exhibited significantly lower PFS than the low expression group, both in lung cancer and colon cancer." (PMID 39107297, 2024). "The activity of ALDH1A1 is a reliable marker of CSCs in several types of solid tumors, including HNSCC,12, 13, 106 lung cancer, PCa,14 and bladder cancer." (PMID 36694633, 2023). "ALDH1A1 knockdown inhibited the invasive ability and tumorigenicity of ALDEFLUOR+ cells, indicating that it is the major isoform in lung cancer." (PMID 37686694, 2023). "Accumulating evidence supports the existence of a CSC phenotype in human lung cancer, and several CSC markers, such as ALDH1A1, CD133, and CD44, have been characterized in lung cancer." (PMID 35087112, 2022). "In this study, we found that ALDH1A1 had tumor suppressor effects in BRCA, CESC, LIHC, Lung cancer, renal cell carcinoma and PAAD, but tumor-promoting effects in SKCM, GBM, THCA and BLCA." (PMID 36484016, 2022). "To understand how dinactin inhibits CSCs properties in the lung cancer cells, we next investigated expression of genes of the well-known lung CSC markers, including ALDH1A1, Nanog, CD133, Oct4, and Sox2 genes by qRT-PCR." (PMID 36551502, 2022). "Standard drugs for lung cancer treatment, cisplatin/gemcitabine,and menadione, reduced ALDH1 expression, while the elimination of ALDH1A1 significantly increased apoptosis and decreased resistance to cisplatin." (PMID 36387165, 2022). "In this study, we focused on ALDH1A1, CD133, Nanog, Oct4, and Sox2, which are transcription factors required for lung cancer pluripotency." (PMID 36551502, 2022). "A current study found that chemoresistant NSCLC patients had upregulated Notch3 expression, which was related to poor prognosis and had augmented levels of CSC markers, ALDH1A1 and CD44, correlating with Notch3 expression in lung cancer biopsies." (PMID 35053430, 2022). "In lung cancer, several CSC markers have been identified and widely utilized, such as CD133, aldehyde dehydrogenase1A1 (ALDH1A1), Oct4 and Nanog." (PMID 34832867, 2021). "Vanillin, a major component in Vanilla planifolia seed, reduces CSC phenotypes in lung cancer cells and downregulates CSC markers CD133, ALDH1A1 and ATP-binding cassette super-family G member 2 (ABCG2)." (PMID 34832867, 2021). "ALDH1A1 and ALDH1A3 were found at higher levels in A459 lung cancer line, higher ALDH1 in gastric CSCs, and higher ALDH also in MCF-7/C6 CSC population selected from MCF-7." (PMID 32012980, 2020). "Immunohistochemically assessed cell positivity for ALDH1A1, SOX2, NANOG, OCT-4, and c-MYC, which are considered as lung cancer stem-like cells markers." (PMID 32500024, 2020). "ALDH1a1 is up-regulated in lung CSC and its expression is positively correlated with the stage and grade of lung cancer patients and related to a poor prognosis." (PMID 28415606, 2017). "Simultaneous knockout of ALDH1A1 and its isozyme ALDH3A1 in lung cancer cell line NCI-H460 inhibited tumor growth in a xenograft model." (PMID 28978015, 2017). "Most significantly, we identified ALDH1A1 as a critical meditator of TAZ-induced tumorigenic and CSC phenotypes in lung cancer." (PMID 28415606, 2017).
lung carcinoma (continued). "Recently, Aldh1a1, a key member of ALDH family, has been shown to be a marker for CSCs in many types of cancers including lung cancer." (PMID 28415606, 2017). "Downregulation of ALDH1A1 and ALDH3A1 has been shown to reduce cell growth and motility in lung cancer cells." (PMID 23236365, 2012). "Genes that were highly affected by the knock-down of ALDH1A1 and ALDH3A1 in A549 lung cancer cell line." (PMID 19025616, 2008). "Additionally, SM-3 treatment resulted in decreased expression of stem cell markers (CD133, CD44, and ALDH1A1) and transcription factors (OCT4, NANOG, and SOX2) in spheroids and organoids from human lung cancer cells by inhibiting the mTOR/pAkt pathway." (PMID 40287470, 2025). "Similarly, gene expressional analysis in lung cancer from TCGA database revealed a positive correlation between GPX2 and CD133, as well as ALDH1A1." (PMID 40533443, 2025). "In addition, in EGFR-mutant lung cancer, S100A9 upregulates the expression of ALDH1A1 and activates the RA signaling pathway." (PMID 40708788, 2025). "However, in lung cancer, the research on ALDH1A1 exhibits two extreme phenomena, particularly in ADC cases, where the restoration of ALDH1A1 expression significantly inhibits the growth of some lung cancer cell lines." (PMID 38589907, 2024). "Another example is that high levels of ALDH1A1 lead to the acquisition of epithelial–mesenchymal transition (EMT) and CSC properties as well as erlotinib resistance through clearance of reactive chlorine species/ROS in lung cancers." (PMID 36694633, 2023). "Moreover, we showed that NAC treatment also restored the expression of ALDH1A1 and ABCG2 in apatinib-treated lung cancer cells." (PMID 33980809, 2021). "RT-qPCR and IHC staining assays here demonstrated that the expression levels of lung cancer markers and cancer stem cell features of lung cells, including Kras, c-Myc, ABCG2, OCT4, SOX2 and Aldh1a1, were markedly increased in lung tissues of PM2.5-challenged mice." (PMID 32554855, 2020). "We also revealed a significant association of high ALDH1A1 with never-smoker status, identifying ALDH1A1 and ALDH1A3 as possibly related to new risk factors in the ~10–20% of lung cancers occurring in never smokers." (PMID 32015486, 2020). "We conducted a meta-analysis based on The Cancer Genome Atlas and Gene Expression Omnibus data and detected genetic alterations in ALDH1A1, ALDH1A3, or ALDH3A1, 86% of which were gene amplification or mRNA upregulation, in 31% of nonsmall cell lung cancers (NSCLCs)." (PMID 32015486, 2020). "The mean difference in the ALDH1A1 concentration between no lung cancer and lung cancer is 2.10 ng/ml, 95% CI: 0.23 ng/ml to 3.98 ng/ml; p=0.028." (PMID 31534455, 2019). "Furthermore, gigantol decreased stemness in the lung cancer cells and reduced well-known lung CSC markers, including CD133 and ALDH1A1." (PMID 29444668, 2018). "Of these genes, human homologs of 4 genes including Inhibin, beta A (INHBA), Kruppel-like factor 5 (KLF5), Serine/threonine/tyrosine kinase 1 (STYK1), and stem cell marker ALDH1A1 are previously shown to be over-expressed in NSCLC and involved in lung cancer progression and tumorigenicity." (PMID 28415606, 2017). "We focused on ALDH1A1, ALDH2 and ALDH3A1 expression among the various isoforms because ALDH1A1 and ALDH3A1 have been shown to be markers of resistance to cyclophosphamide in breast and lung cancer cells and because ALDH2 is a major detoxifying enzyme for reactive aldehydes." (PMID 28881734, 2017). "ALDH1A1 is the most frequent and important ALDH isozyme reported in lung cancer TIC." (PMID 28737489, 2017). "CD133 may be a potential prognostic marker and useful therapeutic target in lung cancer, and co-detection of CD133 with other CSC markers including ALDH1A1 and OCT4 may be more valuable and helpful in clinical application in NSCLC patients." (PMID 24940615, 2014).
lung carcinoma (continued). "Flow cytometric analysis of a panel of lung cancer cell lines and patient-derived tumors revealed the occurrence of a subpopulation of cells with elevated ALDH activity in most non-small cell lung cancers, which correlated with ALDH1A1 expression." (PMID 22110949, 2011). "We further observed that ALDH1A1 positive cells had higher levels of IL-6R, JAK3 and phosphorylated STAT3, suggesting that the lower levels of miR-218 may be responsible for the upregulation of STAT3 signaling in ALDH positive lung cancer cells." (PMID 28830450, 2017). "Indeed, quantitative PCR analysis revealed that the mRNAs of two major ALDH isoforms expressed in the lung cancer cell lines, namely ALDH1A3 and ALDH1A1, were significantly reduced by the TKI treatment, which strongly discouraged their induction by cisplatin (p < 0.05)." (PMID 27486763, 2016). "ALDH1A1 may provide a therapeutic target for developing specific drugs to effectively eradicate lung CSC population and could potentially yield efficient therapeutic approaches for the treatment of lung cancer." (PMID 26783961, 2016). "Interestingly, cell culture model systems and clinical sample studies show that ALDH1A1-positive cancer stem cells promote significant resistance to both EGFR-TKI (gefitinib) and other anticancer chemotherapy drugs (cisplatin, etoposide, and fluorouracil) than ALDH1A1-negative cells in lung cancer." (PMID 29681949, 2018). "Consistent with our findings, it has also been shown by others that overexpression of ALDH1A1 rather than other isoforms (ALDH1A3 and ALDH3A1) increased lung cancer cell transformation and CSC phenotype by activating stem cell drivers Nanog, Oct4, and Sox2." (PMID 28415606, 2017). "In addition, reduction of ALDH1A1 mRNA was also found when TAZ and YAP are knocked out in another lung cancer cell line, H358 (data not shown)." (PMID 28415606, 2017).